Y_RNA (Y RNA )
Gene: Miscellaneous RNA gene on chromosome 4 (27,223,319 to 27,223,427, reverse strand). Ensembl gene ENSG00000222206.
Homologues: Orthologues: chimpanzee Y_RNA (100% identical), macaque Y_RNA (83% identical). Paralogues in human: RNY1P15 (77% identical), Y_RNA (77% identical), Y_RNA (76% identical), RNY1 (75% identical), Y_RNA (75% identical), Y_RNA (74% identical), RNY1P11 (73% identical), Y_RNA (73% identical), RNY1P10 (72% identical), Y_RNA (72% identical), Y_RNA (71% identical), RNY1P13 (70% identical), and 87 more.